TRIM8 (tripartite motif containing 8)
Diseases named in the same sentence as TRIM8 in open-access papers (continued):
Sharing a sentence is not in itself a finding about the gene and the disease.
tumor (continued). "Noteworthy, we found that TRIM8 expression level is significantly decreased in ccRCC compared to matched non-tumour tissue, and such a signature was typical of this more malignant neoplasms, whereas benign oncocytomas (ROs), for instance, didn’t show it." (PMID 28327152, 2017). "We did not treat tumours with anti-miR-17-5p because its inhibitory effects on tumour growth have been reported, while our aim here was to point out the critical role of TRIM8 on tumour growth." (PMID 28327152, 2017). "In addition, the comparison of 28 pairs of tumour-normal tissue samples confirmed that the expression of TRIM8 in tumour tissues was significantly reduced." (PMID 39934162, 2025). "TRIM8 is an E3 ubiquitin ligase that functions as both a tumour suppressor and an oncoprotein." (PMID 41057298, 2025). "Our results suggest that TRIM8 potently suppresses tumour formation and metastasis in vivo." (PMID 39934162, 2025). "However, compared to the mock transfection, TRIM8 transfection inhibited the metastasis of subcutaneous tumour cells from all three cell lines to the liver, and the number of tumour nodules that formed in the liver was significantly reduced." (PMID 39934162, 2025). "Given the antitumour effect of M1 macrophages, we hypothesized that TRIM8 might be a tumour suppressor." (PMID 39934162, 2025). "Furthermore, in a murine xenograft model, TRIM8-overexpressing cells decreased the formation of tumour nodules that metastasized from subcutaneous tumours to the liver in all the A549, CL1-0 and H358 transfectants." (PMID 39934162, 2025). "In addition, the function of TRIM8 is not limited to ubiquitination; it can also act as an oncogene or tumor suppressor in multiple cancers." (PMID 38879525, 2024). "Tripartite motif 8 (TRIM8) is an E3 ligase that plays dual roles in various tumor types." (PMID 38879600, 2024). "On this topic, we focus on TRIM8 and its multiple roles in tumor pathologies." (PMID 35565438, 2022). "In this review, we focused on TRIM8 and its multiple roles in tumor pathologies." (PMID 35565438, 2022). "Moreover, we show how TRIM8 functions are not limited to ubiquitination, and contrasting data highlight its role either as an oncogene or as a tumor suppressor gene, acting as a “double-edged weapon”." (PMID 33807506, 2021). "For example, TRIM8 shows multiple functions in embryonic development and tumours." (PMID 33858426, 2021). "In this review, we discuss the role of TRIpartite Motifs (TRIM) proteins in cancers and in CRC chemoresistance, focusing on the tumor-suppressor role of TRIM8 protein in the reactivation of the CRC cells sensitivity to drugs currently used in the clinical practice." (PMID 33673719, 2021). "TRIM8 was reported to be a tumor suppressor in glioma and renal cell carcinoma." (PMID 31781486, 2019).
tumor (continued). "As tumours develop and progress, these protective and cytostatic effects of TRIM8 are often lost." (PMID 29182544, 2017). "Based on the in vitro experiments, we hypothesized that TRIM8 over-expression might inhibit tumour growth in vivo, and attempted to demonstrate it by injecting human cancer cells into nude mice." (PMID 28327152, 2017). "Although some studies point to the tumour suppressor role of TRIM8, a number of oncogenic mechanisms have been proposed concerning a TRIM8 role in the regulation of inflammatory pathways, including the NF-κB pathway, and therefore in supporting tumour onset and progression." (PMID 29182544, 2017). "The TRIM8 deficit, observed in patients affected by ccRCC, was explained by the up-regulation of the miR-17-5p and miR-106b-5p members of the miR-17-92 family, whose overexpression has an oncogenic effect by promoting tumour cell proliferation." (PMID 29182544, 2017). "Tertiles of TRIM8 expression were calculated within each tumor grade, separately." (PMID 26077989, 2015). "We found a linear trend of TRIM8 copy number across tumor grades (p = 0.025)." (PMID 26077989, 2015). "In the attempt to translate our findings in vivo and set the basis for the use of TRIM8 as enhancer of the chemotherapy efficacy, we investigated whether in tumours highly resistant to chemotherapy, TRIM8 expression levels were lower compared to normal tissue." (PMID 25277184, 2014). "Accordingly TRIM8 protein levels in tumour samples were lower compared to non-tumour counterpart." (PMID 25277184, 2014). "The observation of TRIM8 mediated increase in cell motlity and clonogenic ability further supports that TRIM8 may act as tumor promoter in specific conditions." (PMID 23152791, 2012). "TRIM8 could also mediate K63-linked ubiquitination of TAK1, hence activating TNF-α, IL-1β and NF-κB signaling, which cooperatively promote malignant phenotypes of tumor cells." (PMID 38879600, 2024). "Therefore, the down-regulation of the MYCN-miR-17-92 network in order to increase the TRIM8 expression level in cancer cells represents an interesting approach to inhibit uncontrolled cell proliferation and tumour growth and sensitize cancer cells to chemo- and radiotherapy in vivo." (PMID 30974870, 2019). "In the TCGA GBM data, TRIM8 expression was highly correlated with nearly all stem cell markers and transcription factors that we investigated, leading to our hypothesis that TRIM8 may have a functional role in supporting stem cell properties in this tumor type." (PMID 28100038, 2017). "TRIM8 signaling may then switch to promote cancer progression, invasion, and tumour metastasis." (PMID 29182544, 2017). "Approaches that inhibit TRIM8-mediated K63 ubiquitination and PGK1-regulated glycolysis likely increase the efficacy of tumor angiogenesis treatment." (PMID 41184227, 2025). "Conversely, compared to shLacZ, TRIM8 knockdown significantly promoted tumorigenesis and slightly facilitated the spread of CL1-0 tumour cells to the liver." (PMID 39934162, 2025). "However, whether TRIM8 regulates tumor cell metabolism remains unknown." (PMID 41184227, 2025). "TRIM8 and UHRF2 expression in the tumor group was significantly higher than that in the normal group." (PMID 38879525, 2024). "In this study, we discovered that the expression of TRIM8 was upregulated in HCC tissues, and was positively correlated with aggressive tumor behavior of HCC and shorter survival of HCC patients." (PMID 38879600, 2024).
tumor (continued). "Several studies reported that TRIM8 has a key role both as an oncogene by affecting the NF-kB and JAK-STAT pathways and as a tumor suppressor." (PMID 35565438, 2022). "In contrast to the oncogenic action of the TRIMs described so far, TRIM67, TRIM58 and TRIM8 are downregulated in CRC, playing a tumor suppressor role." (PMID 33673719, 2021). "In contrast, a few members including TRIM8, TRIM15, TRIM24, and TRIM40 are characteristically downregulated in CRC and exert tumor-suppressive activities." (PMID 33066016, 2020). "We found a statistically significant lower TRIM8 relative expression in grade IV, when compared with grades II and III (p < 0.001) in both tumor tissues and cell lines." (PMID 26077989, 2015). "Consequently, TRIM8-mediated PGK1 K63 ubiquitination and ACAT1-dependent PGK1 acetylation are required for glycolysis, which promotes lactate accumulation and tumor angiogenesis." (PMID 41184227, 2025). "Compared to the mock control group, the TRIM8-transfected group exhibited a 2.7-fold decrease in tumour weight, but subcutaneous tumour growth was not different between the A549 and H358 cells." (PMID 39934162, 2025). "We demonstrated that TRIM8 stabilizes PGK1 through K63 ubiquitination and recruits ACAT1, driving PGK1 acetylation, thereby enhancing PGK1-mediated glycolysis and ultimately leading to lactate accumulation and tumor angiogenesis." (PMID 41184227, 2025). "TRIM8 and its induced K63 ubiquitination promote the interaction of PGK1 with ACAT1, thereby facilitating PGK1 acetylation and downstream glycolysis for lactate accumulation and tumor angiogenesis." (PMID 41184227, 2025). "Because OC is primarily a tumor of epithelial origin, the expression of TRIM proteins was analyzed in epithelial cells, and the eight most highly expressed genes (TRIM28, TRIM27, TRIM33, TRIM38, TRIM47, TRIM56, TRIM8, and TRIM24) were determined." (PMID 38881325, 2024). "The CSCs score showed the superior characteristics of tumor stem cells in TRIM8 high expression group compared with normal control group." (PMID 36353542, 2022). "Furthermore, this paper focuses on TRIM8, a member of the TRIM family proteins, describing its role both as a tumor suppressor and as an oncogene." (PMID 35565438, 2022). "Importantly, we discovered TRIM8, DTX2, and TRAF5 as the most vital contributors from the RNF family, which were related to immune infiltration in LGG tumor immune landscape." (PMID 35223862, 2021). "TRIM8 also has a role in maintaining stemness and self-renewing capabilities of GSC, which contribute to the rapid growth, therapeutic resistance, and clinical recurrence of these aggressive tumours." (PMID 29182544, 2017). "Targeting either TRIM8 or STAT3 could effectively disrupt the positive feedback loop and attenuate the self‐renewal capacity and tumor propagation of GBM." (PMID 28100038, 2017). "Indeed, by targeting either TRIM8 or STAT3, researchers would be able to disrupt their positive feedback loop and attenuate the self-renewal capacity and tumour propagation of GBM." (PMID 29182544, 2017). "By comparing tumour and corresponding healthy tissues, we found that in patients affected by ccRCC, TRIM8 expression level is decreased, while no alterations were observed in ROs." (PMID 25277184, 2014). "On average tumour samples expressed TRIM8 at a lower level (3.2-fold; p-value = 2.33E-06) than non-tumour renal epithelial tissue." (PMID 25277184, 2014).
tumor (continued). "To determine whether PGK1 K63 ubiquitination-induced lactate accumulation affects tumor angiogenesis, we performed endothelial cell migration and tube formation assays to test whether PGK1 silencing would recapitulate the effect of TRIM8 suppression on angiogenesis." (PMID 41184227, 2025). "Considering the variation of TRIM8 expression in each ccRCC tissue pair and Fuhrman grade, no variation was detected indicating that the down-regulation of TRIM8 expression seems to be independent from the severity of this type of tumour." (PMID 25277184, 2014). "Our findings support the role of TRIM8 as a potential oncogene in GBM through its regulation of PIAS3‐STAT3 and GSC stemness, rather than a tumor suppressor, as might be expected by its frequent deletion." (PMID 28100038, 2017). "A recent publication suggested that TRIM8 might act as a tumor suppressor in GBM, although these studies did not confirm the protein expression of TRIM8." (PMID 28100038, 2017).
cancer (27 papers, 2012 to 2025). A tumor composed of atypical neoplastic, often pleomorphic cells that invade other tissues. "To further investigate the relationship of TRIM8 expression with immunomodulators, we first analyzed the association between the expression of TRIM8 and immuneinhibitors across human cancers." (PMID 35368651, 2022). "The result showed that the expression levels of TRIM8 was significantly associated with immunoinhibitors in a variety of cancers." (PMID 35368651, 2022). "Another important cellular function in which TRIM8 is involved is the regulation of innate immunity, an aspect again closely linked to cancer." (PMID 29182544, 2017). "TRIM8 belongs to the Tripartite Motif protein family, whose members have been implicated in a variety of processes like development, differentiation and cancer." (PMID 25277184, 2014). "The low chemotherapy response characterising ccRCC and CRC prompted us to investigate whether miR-17-5p and miR-106b-5p might contribute to the chemotherapy resistance due to the TRIM8 protein loss, in the two paradigmatic models of these cancers." (PMID 28327152, 2017). "The E3 ligase TRIM8 plays important but divergent roles in various types of cancer via multiple mechanisms." (PMID 41184227, 2025). "Since invasion is the first step in the initiation of cancer metastasis, we assessed the effect of TRIM8 on cell invasion via a Matrigel invasion assay." (PMID 39934162, 2025). "Recently, more attention has been given to the functions of TRIM8 in cancer progression: TRIM8 regulates critical cellular functions in cancers, including proliferation and migration, gene transcription, the cell cycle, and stemness." (PMID 41184227, 2025). "A dual role of TRIM8 in cancers as an oncogene or a tumor suppressor gene has been elaborated in previous studies." (PMID 38879600, 2024). "RNA sequencing revealed that TRIM8 knockout suppresses several cancer-related pathways, including Wnt/β-catenin and TGF-β signaling in HepG2 cells." (PMID 38879600, 2024). "Analysis based on RNA-Seq and TCGA data further showed that TRIM8 participates in a series of cancer-related pathways and functions as an important regulator of EMT and cell cycle in HCC." (PMID 38879600, 2024). "As an E3 ligase, TRIM8 mediates the ubiquitination of diverse substrates in the different kinds of carcinoma." (PMID 38879600, 2024). "In fact, during genotoxic stress, TRIM8 can allow a proliferative advantage to cancer cells by increasing autophagy flux through lysosomal biogenesis and inactivating the cleaved Caspase-3 subunit to inhibit cell death induced by genotoxic stress." (PMID 35565438, 2022). "TRIM8 affected the degradation of ∆Np63α in both a proteasomal and caspase-1-dependent expertise pathway, opposing the proliferation of cancer cells." (PMID 35565438, 2022). "To evaluate TRIM8 expression in human cancer, we used Oncomine databases to analyze the differential expression of the mRNA levels in cancer and normal tissues." (PMID 35368651, 2022). "A close relationship between TRIM8 expression and abundance of 28 TILs in different types of cancer was shown." (PMID 35368651, 2022).